CHD1 (chromodomain helicase DNA binding protein 1)
Description:
ATP-dependent chromatin-remodeling factor which functions as substrate recognition component of the transcription regulatory histone acetylation (HAT) complex SAGA. Regulates polymerase II transcription. Also required for efficient transcription by RNA polymerase I, and more specifically the polymerase I transcription termination step. Regulates negatively DNA replication. Not only involved in transcription-related chromatin-remodeling, but also required to maintain a specific chromatin configuration across the genome. Is also associated with histone deacetylase (HDAC) activity (By similarity). Required for the bridging of SNF2, the FACT complex, the PAF complex as well as the U2 snRNP complex to H3K4me3. Functions to modulate the efficiency of pre-mRNA splicing in part through physical bridging of spliceosomal components to H3K4me3. Required for maintaining open chromatin and pluripotency in embryonic stem cells (By similarity).
Synonyms: CHD-1; PILBOS
Tractability: Small molecule: a structure with a bound ligand is known. PROTAC: ubiquitination databases record sites on it; its protein half-life has been measured.
Target class: Enzyme; Hydrolase
Gene: Protein-coding gene on chromosome 5 (98,853,985 to 98,929,007, reverse strand). Ensembl gene ENSG00000153922.
Subcellular location: Nucleus; Cytoplasm
Subcellular location (Human Protein Atlas): Nucleoplasm; Nucleoli fibrillar center; Vesicles
Pathways (Reactome):
Chromatin organization: CHD1 and CHD2 subfamily
Signal Transduction: Estrogen-dependent gene expression
Gene Ontology:
Molecular function: histone H3K4me3 reader activity; protein binding; ATP hydrolysis activity; ATP-dependent chromatin remodeler activity; chromatin binding; DNA binding; histone binding; ATP binding
Biological process: chromatin remodeling; host-mediated activation of viral transcription; nucleosome organization
Cellular component: cytoplasm; nuclear chromosome; nucleus; chromatin; nucleoplasm
Genetic constraint (gnomAD): Loss-of-function variants: 13 observed, 99.74 expected, observed/expected ratio (o/e) 0.13, 90% interval 0.084 to 0.21. The upper end of that interval is the gene's LOEUF score, 0.21, which puts it in group 1 of 6, group 1 being the genes least tolerant of losing a copy. Missense variants: 860 observed, 1,167.8 expected, observed/expected ratio (o/e) 0.74, 90% interval 0.69 to 0.78. Synonymous variants: 355 observed, 382.98 expected, observed/expected ratio (o/e) 0.93, 90% interval 0.85 to 1.01.
Gene-disease validity (ClinGen):
ClinGen rates the evidence that CHD1 causes each of these diseases.
complex neurodevelopmental disorder (autosomal dominant): Limited. A disorder that involves more than one phenotype associated with the central nervous system, including but not limited to intellectual disability, autism, and seizures (epilepsy).
Homologues: Orthologues: chimpanzee CHD1 (99% identical), macaque CHD1 (99% identical), dog CHD1 (98% identical), pig CHD1 (98% identical), mouse Chd1 (96% identical), rat Chd1 (95% identical), guinea pig CHD1 (92% identical), tropical clawed frog chd1 (86% identical), rabbit CHD1 (81% identical), zebrafish chd1 (79% identical). Paralogues in human: CHD2 (62% identical), CHD5 (24% identical), CHD3 (23% identical), CHD9 (23% identical), CHD7 (23% identical), CHD4 (23% identical), CHD6 (22% identical), CHD8 (22% identical), SRCAP (21% identical), SMARCA4 (21% identical), SMARCA2 (20% identical), SMARCA1 (19% identical), and 18 more.
Diseases named in the same sentence as CHD1 in open-access papers:
CHD1 is named in the same sentence as 64 diseases in open-access papers, as found by Europe PMC text mining. Sharing a sentence is not in itself a finding about the gene and the disease. The quoted sentences say what the papers report.
prostate carcinoma (69 papers, 2013 to 2026). A carcinoma that arises from epithelial cells of the prostate gland. "They found that loss of either MAP3K7, a kinase involved in inflammatory signaling, or CHD1, a chromatin-remodeling factor, rendered previously resistant prostate cancer cells highly susceptible to VSV infection and oncolysis." (PMID 41294689, 2025). "The loss of CHD1 is significant as it has been linked to early resistance to anti-androgen treatment in prostate cancer." (PMID 40606443, 2025). "We created CRISPR edited, CHD1 deficient prostate cancer cell lines for genomic, drug sensitivity and functional homologous recombination (HR) activity analysis." (PMID 38645014, 2024). "Mutation in the CHD1 gene, encoding Chromodomain Helicase DNA-binding Protein 1, is also reported in prostate cancer and breast cancer." (PMID 39057032, 2024). "In prostate cancer patients, CHD1 loss was associated with a shorter time to PSA recurrence, suggesting its potential as a prognostic biomarker." (PMID 36776288, 2023). "used AR-overexpressing LNCaP models and showed that CHD1 loss renders human prostate cancer cells more resistant to AR inhibitors in vitro and in vivo in castrated mice." (PMID 36776288, 2023). "CHD1 has been shown to active NF-κB in PTEN-deficient prostate cancer cells, which in turn promotes the secretion of IL-6." (PMID 37190171, 2023). "This offers new insights into synthetic lethal interactions with CHD1 and potential therapeutic vulnerabilities in prostate cancers containing CHD1 deficiency." (PMID 36776288, 2023). "Along the same line, Jillson and colleagues showed that co-suppression of MAP3K7 and CHD1 causes androgen-independent growth of prostate cancer cells and promotes resistance to AR inhibitor enzalutamide." (PMID 36776288, 2023). "Recent studies found that SPOP mutations and CHD1 deletion sensitize prostate cancer cells to DNA damage inducers and show synergistic effects on the DNA damage repair." (PMID 36776288, 2023). "In contrast, PTEN-deficient prostate cancer cells stabilise CHD1 protein and lead to its interaction with H3K4me3 and transcriptional activation of NF-κB downstream genes to cause the progression of prostate cancer." (PMID 37533462, 2023). "Given that co-occurrence of SPOP mutations and CHD1 deletion define a distinct molecular subtype of prostate cancer, further studies are needed to assess if they have synergistic effects in response to DNA-damaging therapies." (PMID 36776288, 2023). "CHD1 has been documented as an essential tumor suppressor and has a strong association with prostate cancer." (PMID 36361605, 2022). "The chromatin modifying helicase CHD1 is a chromatin remodeler that has been implicated as a tumor suppressor in primary prostate cancer, as CHD1 is recurrently deleted in primary prostate tumors." (PMID 36212399, 2022). "Mutations and homozygous deletions in CHD1 have been identified in prostate cancers, particularly in Chinese patients, where the deletion state was identified in 18% of the cohort." (PMID 36361605, 2022). "The DNA repair defects caused by loss of chromodomain helicase DNA binding protein 1 (CHD1) significantly enhanced prostate cancer therapeutic responsiveness." (PMID 33407221, 2021). "Here, we examine the role in DSB repair of the ATP-dependent chromatin remodeler Chd1, which is frequently mutated in prostate cancer." (PMID 34520455, 2021). "The CHD1 gene is frequently mutated in prostate cancer where these mutations are associated with a poor prognosis." (PMID 34520455, 2021). "Although this study was focused solely on identifying enzalutamide resistance mechanisms linked to CHD1 loss, it is remarkable that all four of the TFs identified have been previously implicated in advanced prostate cancer progression." (PMID 32220301, 2020). "This pattern is disrupted in the setting of CHD1 loss, where aberrant AR cistromes are observed that more closely resemble those seen in prostate cancers." (PMID 32220301, 2020).
prostate carcinoma (continued). "We find that loss of CHD1, a commonly deleted prostate cancer gene, confers resistance to the next-generation antiandrogen enzalutamide by establishing a state of chromatin dysregulation." (PMID 32220301, 2020). "We identified CHD1 loss as a cause of antiandrogen resistance in an in vivo small hairpin RNA (shRNA) screen of 730 genes deleted in prostate cancer." (PMID 32220301, 2020). "The CHD1 gene encodes the chromo-domain helicase DNA-binding protein 1 and, as above discussed, is one of the genes most frequently deleted or mutated in prostate cancer." (PMID 31366128, 2019). "The analysis of large-scale genomic studies of the TCGA and other prostate cancer databases provided evidence that in the large majority of patients CHD1 loss and PTEN deletion (as well as AKT1, AKT2, AKT3, and PIK3CA gene alterations) were mutually exclusive." (PMID 31366128, 2019). "Loss of CHD1 has been implicated in the initiation of ETS prostate cancers, preventing ERG rearrangement in the prostate and thus explaining the exclusivity between ETS positivity and homozygous loss of CHD1." (PMID 31366128, 2019). "It is important to note that loss of CHD1, observed in ~15% of primary prostate cancer cases, is rarely deleted in other cancer types, suggesting a prostate-specific role as a tumor suppressor of prostate tumorigenesis." (PMID 31366128, 2019). "At molecular level, two main genomic abnormalities define two molecular subgroups of cribriform prostate cancers: SPOPmut, which is associated with CHD1 and MAP3K codeletions, and (ii) PTENloss, which is mutually exclusive with SPOPmut." (PMID 31366128, 2019). "A recent study demonstrated that loss of CHD1 causes DNA repair defects and has the potential to enhance prostate cancer therapeutic responsiveness." (PMID 28649742, 2017). "Loss of human CHD1 is linked to prostate cancer, and mouse Chd1 is required for maintenance of stem cell pluripotency and early embryogenesis." (PMID 26596648, 2015). "Notably, the loss of CHD1 function is observed in around 8%–18% of prostate cancer cases, causing widespread alterations in gene expression in a cellular context-specific manner." (PMID 41168190, 2025). "In addition, the analysis showed chromosomal alterations commonly associated with prostate cancer, such as losses on chromosomes 8p, 10p, and 12p, and focal losses on chromosomes 1q, 4p, and 5q21.3 (CHD1)." (PMID 40606443, 2025). "In the context of cancer biology, some CHD1-proximal lncRNAs have been linked to microRNA and androgenic receptor (AR) mRNA, which might participate in gene repression and prostate cancer, respectively." (PMID 41168190, 2025). "In addition to analyzing patient derived next generation sequencing data, we performed FISH based confirmatory studies of Chromodomain helicase DNA-binding protein 1 (CHD1) loss on prostate cancer tissue microarrays." (PMID 38645014, 2024). "CHD1 deficient prostate cancer cells, however, showed higher sensitivity to talazoparib." (PMID 38645014, 2024). "Although these cases appear to result from clonal expansion of prostate cancer cells undergoing incomplete Chd1 deletion, future study is needed to identify potential second-site suppression events that may underlie CHD1 bypass." (PMID 36776288, 2023). "CHD1 loss is also associated with chromosomal and genomic instability in prostate cancers, and DDR defects may serve as one of the mechanisms." (PMID 36776288, 2023). "Notably, the upregulation of transcription factors of GR, BRN2, TBX2, and NR2F1 was found to mediate the resistance to enzalutamide in CHD1-deficient prostate cancer, since inhibition of each factor re-sensitizes CHD1 loss prostate tumors to AR inhibitor." (PMID 36776288, 2023). "The CHD1-PTEN synthetic lethal relationship may even be exploited further using immune checkpoint inhibition given CHD1’s role in maintaining an elevated level of myeloid-derived suppressor cells in Pten-deficient prostate cancers." (PMID 36830628, 2023).
prostate carcinoma (continued). "Nevertheless, better understanding their interactions and underlying mechanisms might provide novel therapeutic strategies for MAP3K7/CHD1 loss prostate cancer." (PMID 36776288, 2023). "Besides, recent studies in metastatic prostate cancer patients showed that CHD1 deletion is associated with HR deficiency-related mutational signatures." (PMID 36776288, 2023). "Notably, CHD1 deletion is an early prostate cancer event, resulting in the loss of integrity of the AR cistrome." (PMID 36212399, 2022). "CHD1 loss in vitro and in vivo similarly accompanied enzalutamide-resistant prostate cancer growth." (PMID 36212399, 2022). "Additionally, CHD1 is mutated in prostate cancer and through TAT-SF1, Merlin interacts with the U2 snRNP complex of the spliceosome, whose components are also frequently mutated in several cancer types." (PMID 34424918, 2021). "Of note, CHD1 is the second most frequently mutated gene in prostate cancer, after PTEN24,25." (PMID 34381042, 2021). "CHD1 drives immune suppression in PTEN-deficient prostate cancer." (PMID 33663617, 2021). "In PTEN-deficient prostate cancer, prostate-specific deletion of CHD1 resulted in markedly delayed tumor progression and prolonged survival, which was associated with a reduction in MDSCs and an increase in CD8+ T cells through IL-6, a key transcriptional target of CHD1." (PMID 35003065, 2021). "In closing, it is worth considering the clinical implications of CHD1 loss in prostate cancer." (PMID 32220301, 2020). "Furthermore, their upregulation in the context of CHD1 loss was reversible, as revealed by doxycycline-regulated CHD1 shRNA knockdown and was evident in three other AR-positive human prostate cancer cell lines." (PMID 32220301, 2020). "Mutations in CHD1 are frequently associated with prostate cancers." (PMID 33424937, 2020). "This intriguing finding may be explained assuming that CHD1 expression may be required for the progression of prostate cancer driven by PTEN loss." (PMID 31366128, 2019). "A significant proportion of CHD1-deleted prostate cancers coexpress SPOP mutations." (PMID 31366128, 2019). "Interestingly, in PTEN-deficient prostate cancer, the inactivation of CHD1 dramatically reduces proliferation and survival, due to its regulatory role on the tumor necrosis factor/nuclear factor kappa-light-chain-enhancer of activated B cells pathway." (PMID 28486411, 2017). "CHD1 loss may contribute to worse outcome of prostate cancer in African American men." (PMID 38645014, 2024). "Interestingly, the CHD1 loss/deletion was more frequent among Chinese primary prostate cancer patients than in corresponding Caucasian patients (31% vs. 16%); conversely, Chinese prostate cancers exhibited only 6% of ERG gene rearrangements." (PMID 31366128, 2019). "The chromatin remodeler CHD1, a regulator of gene activity and potential drug target in prostate cancer (PCa), contains a tandem chromodomain (tCD) binding histone H3 trimethylated at lysine 4 (H3K4me3)." (PMID 42085696, 2026). "Prospective clinical trials are required to confirm the influence of CHD1 deletion on the response to castration, abiraterone, enzalutamide, and other anti-androgen therapies in both hormone-sensitive and resistant prostate cancer." (PMID 40606443, 2025). "CHD1 has been shown to be critical to the signalling of DNA damage and has been shown to act as a tumour suppressor in prostate cancer." (PMID 40135438, 2025). "Prostate cancer organoids retain parental genetic features, including TMPRSS2–ERG fusion, SPOP mutation, SPINK1 overexpression, and CHD1 loss." (PMID 39309690, 2024). "In this Review, we summarize the biochemical properties and dysregulation of CHD1 in cancer cells, and then discuss CHD1’s roles in different contexts of prostate cancer, with an emphasis on its crosstalk with diverse signaling pathways." (PMID 36776288, 2023).
prostate carcinoma (continued). "Cell proliferation, survival, and tumorigenic potential were suppressed with the inhibition of CHD1 in PTEN-deficient breast and prostate cancers." (PMID 37533462, 2023). "In occurrence with CHD1 deletion, SPOP mutations define a distinct prostate cancer subtype, characterized by genomic instability, increased AR transcriptional activity, absence of ERG rearrangements, and increased DNA methylation." (PMID 36776288, 2023). "Mechanistically, CHD1 is stable in PTEN-null prostate cancer cells and interacts with the active epigenetic marker trimethylation of H3K4me3 in the IL-6 gene." (PMID 37190171, 2023). "Recent epidemiology and genomics studies of prostate cancer in Asian men uncovered that CHD1 is more often deleted (18%) in the East Asian population with localized prostate cancer than in Western patients." (PMID 36776288, 2023). "To this end, we established ESS2-knockdown PC3 prostate cancer cells and found that these cells showed reduced proliferation accompanied by aberrant mRNA expression of nuclear factor (NF)-κB/CHD1 and prostate cancer-related genes." (PMID 37524814, 2023). "Our prior studies in prostate cancer demonstrated that PTEN-AKT-GSK3β signaling promotes CHD1 protein degradation via the β-TrCP-mediated ubiquitination-proteasome pathway." (PMID 36776288, 2023). "We summarize CHD1’s biochemical properties and dysregulation in cancer cells, as well as discuss its biological functions in different contexts of prostate cancer, emphasizing its crosstalk with diverse signaling pathways." (PMID 36776288, 2023). "Phenocopying CHD1 depletion, pharmacological inhibition of IL-6 and dual blockade of PD-1/CTLA-4 showed synergistic effects in preclinical models of PTEN-deficient prostate cancer." (PMID 36776288, 2023). "Using prostate cancer cell lines and GEM models, several studies reported that CHD1 loss causes defects in HR-mediated DNA damage repair (DDR) and increases sensitivity to DNA-damaging therapies." (PMID 36776288, 2023). "Prospective clinical trials are needed to validate the impact of CHD1 deletion on response to castration, abiraterone, enzalutamide, and other antiandrogen drugs in both hormone-sensitive and -resistant prostate cancers." (PMID 36776288, 2023). "In prostate cancer, CHD1 co-localizes with H3K4me3 to the promoters of actively transcribed genes, while CHD1 depletion reduces H3K4me3 marked genes, alters the chromatin assembly across the genome, and reprograms the global transcription." (PMID 36776288, 2023). "Next, we evaluated correlations between ESS2 and CHD1 target gene expression in patients with prostate cancer using the R2 database." (PMID 37524814, 2023). "CHD1 deletion often co-occurs with missense mutations in SPOP (speckle-type BTB/POZ protein) and defines a new molecular subtype of prostate cancer, characterized by increased DNA methylation and homogeneous gene expression patterns." (PMID 36776288, 2023). "Our prior studies in xenograft and GEMM models established CHD1 as a synthetic essential gene and potential therapeutic target in prostate cancers containing PTEN defects." (PMID 36776288, 2023). "Given the frequent alterations and dysregulation of CHD1 in prostate tumors, in this section, we review CHD1’s biological functions in prostate cancer with an emphasis on its crosstalk with different genetic alterations and diverse signaling pathways." (PMID 36776288, 2023). "In this Review, we focus on the chromatin remodeler CHD1 that plays multifaceted roles in prostate cancer." (PMID 36776288, 2023). "In the past decade, large-scale cancer genome studies showed recurrent deletions of the CHD1 gene in ~8% of prostate cancer." (PMID 36776288, 2023).